NOS3 (nitric oxide synthase 3)
Diseases named in the same sentence as NOS3 in open-access papers (continued):
Sharing a sentence is not in itself a finding about the gene and the disease.
cardiovascular disease (continued). "Sequence variations have been reported since the cloning of NOS3; variations may result in reduced or excessive production of NO and contribute to cardiovascular diseases." (PMID 22470539, 2012).
tumor (76 papers, 1998 to 2026). "These correlations suggest that NOS3 dysregulation is associated with increased ER stress in high-grade PCa, potentially contributing to tumor progression by amplifying the stress response." (PMID 41198652, 2025). "We analyzed the association between NOS3 expression and tumor stage in 6 tumor types that had stage information in TCGA." (PMID 33747912, 2021). "The first evidence of the association of NOS3 polymorphisms with circulating tumor cells was demonstrated between the intron 4 polymorphism and the folate hydrolase – prostate-specific membrane antigen (FOLH1) expression in the peripheral blood." (PMID 18823560, 2008). "The polymorphisms in the promoter region of NOS3 gene may be responsible for variations in the plasma NO, which may promote cancer progression by providing a selective growth advantage to tumor cells by angiogenic stimulus and by direct DNA damage." (PMID 18823560, 2008). "As expected, NOS3 knockdown diminished the synergistic antitumor effect of Cory and Sora, as evidenced by tumor weight and volume measurements." (PMID 41233831, 2025). "Conversely, some studies have shown that NOS3 overexpression can suppress tumor cell proliferation and induce cell death via increased oxidative/nitrosative stress." (PMID 41233831, 2025). "NOS3 expression has also been observed in various tumor types, and its function appears context-dependent, acting as either a tumor promoter or suppressor depending on cancer type and microenvironment." (PMID 41233831, 2025). "Mice with NOS3 knockdown tumors showed increased tumor volume and weight when administered Cory, compared to control tumors." (PMID 41233831, 2025). "Next, we detected the protein expression of NOS3 in tumor tissues treated with Sora and/or Cory by Western Blot." (PMID 41233831, 2025). "In our study, NOS3 knockdown attenuated the synergistic anti-tumor effects of Cory and sorafenib, supporting a role for NOS3 in mediating drug sensitivity in HCC." (PMID 41233831, 2025). "Among them, for example, is NOS3, nitric oxide synthase, which is highly expressed in a variety of human cancers and plays a key role in tumor progression." (PMID 38297316, 2024). "Research has discovered that in CRC cells, highly phosphorylated nitric oxide synthase 3 (NOS3) is crucial for tumor cells to resist oxaliplatin." (PMID 39763669, 2024). "Our research findings indicate that, in addition to the previously identified regulatory mechanisms of NOS3 within endothelial cells themselves, we have discovered that endothelial cells can uptake NOS3 from tumor-secreted exosomes." (PMID 38802855, 2024). "Previous research has shown that NOS3 inhibits apoptosis and promotes tumor proliferation, invasiveness, and immunosuppression." (PMID 37124616, 2023). "We analyzed NOS3 mRNA expression levels across tumors and their corresponding normal tissues in 28 tumor types that had three or more normal tissues data based on TCGA and GTEx database." (PMID 33747912, 2021). "In our samples, the expression of NOS-3 seems to be as high in the case of tissues surrounding the tumor as in the very centre of the lesion." (PMID 33920190, 2021). "For example, ursolic acid, which has an anti-tumor effect, has been proven to promote NOS3 phosphorylation and inhibit NOS3 uncoupling, thereby preventing doxorubicin-induced cardiac toxicity." (PMID 33747912, 2021). "We found that among the six tumor types expressed higher NOS3 level, NOS3 mRNA was related to a worse prognosis in patients with STAD (median survival: 1,686 vs. 801, p = 0.0133385, HR = 1.394)." (PMID 33747912, 2021). "Analyses of TCGA data showed that NOS3 expression increased in six tumor tissues compared with their corresponding normal tissues." (PMID 33747912, 2021). "Univariate cox regression suggested that NOS3 expression (HR = 2.166, 95% CI: 1.065–4.405, p = 0.033) and tumor stage (HR = 4.775, 95% CI: 2.213–10.302, p < 0.001), were related to OS." (PMID 33747912, 2021).
tumor (continued). "In our research, expression level of NOS3 was significantly increased in STAD tumor tissues, and its expression level was the highest among the tumor types and cancer cell lines involved in this study." (PMID 33747912, 2021). "Multivariate cox regression indicated that NOS3 expression (HR = 2.416, 95% CI: 1.181–4.941, p = 0.016) and tumor stage (HR = 5.101, 95% CI: 2.353–11.058, p < 0.001) were independent prognostic factors for OS." (PMID 33747912, 2021). "We evaluated the relation of the NOS3 rs2070744 genotypes to the tumor response, progression-free survival (PFS), and overall survival (OS) as the response for lenvatinib." (PMID 33051476, 2020). "We also assessed gene expression of various factors associated with the suppressive function of MDSCs including S100A8, S100A9, Nos3, Arg1 and Arg2 in BM-MDSCs compared to G-MDSCs from the tumor, spleen and lungs of tumor-bearing mice." (PMID 29677215, 2018). "LMM3 cells express COX-1, COX-2, NOS2, NOS3 and arginase II, involved in angiogenesis and tumor cell migration." (PMID 18261208, 2008). "However, in the hypoxic tumor microenvironment, NOS3 can become uncoupled and produce superoxide, contributing to elevated ROS levels." (PMID 41233831, 2025). "For instance, NOS3 knockout mice could help determine the impact of NO depletion on tumor angiogenesis and progression." (PMID 39859471, 2025). "NOS3/cGMP facilitates tumour angiogenesis and signal transduction." (PMID 38136342, 2023). "Studies have shown that NOS3 may play an important role in tumor progression via angiogenesis or apoptosis." (PMID 36016606, 2022). "The expression of NOS3 was highly variable across different normal tissues and tumor tissues." (PMID 33747912, 2021). "NOS3 inhibition by the inhibitor N(G)-nitro-L-arginine methyl ester (L-NAME) could suppress pancreatic ductal adenocarcinoma cancer (PDAC) tumor growth." (PMID 33747912, 2021). "Among the six tumor types, NOS3 related to advanced tumor stage in SKCM." (PMID 33747912, 2021). "In BRCA, we also found that the higher expression of NOS3 mRNA was related to advanced tumor stage." (PMID 33747912, 2021). "This interaction could sustain the VEGFR2 pathway as well as stimulate NOS3 signaling, and ultimately promote angiogenesis in tumor." (PMID 33747912, 2021). "Considering that tissue-based RNA expression detection might be complicated by the non-tumor tissues that are adjacent to tumor cells, we analyzed NOS3 mRNA expression in 1457 cell lines derived from 26 tumor types in the CCLE database." (PMID 33747912, 2021). "However, because of the limited number of studies on NOS3 expression in malignant tumors, NOS3 functions in tumor pathogenesis and development are still not fully understood." (PMID 33747912, 2021). "Furthermore, we analyzed fold change (FC) of NOS3 mRNA between tumor and corresponding normal tissues." (PMID 33747912, 2021). "And in 33 tumor types involved in this study, NOS3 mRNA was expressed highest in STAD." (PMID 33747912, 2021). "The result of t-test showed that in SKCM, patients with advanced tumor stage expressed higher NOS3 mRNA levels, indicating that NOS3 mRNA might positively related to later tumor stage." (PMID 33747912, 2021). "The results showed that RPII remarkably decreased energy metabolism, and type III nitric oxide synthase 3 (NOS3) may be a target to block tumor growth." (PMID 35047513, 2021). "Although NOS expression is associated with cancer progression and metastasis, recent studies have suggested that NOS3 may inhibit tumor growth, invasion, and angiogenesis, particularly in breast cancer, and CRC." (PMID 31195721, 2019). "However, patients with NOS3‐rs2070744 and NOS3‐rs1799983 genotypes showed lower tumor specific mortality and progression rates after BCG treatment." (PMID 30907072, 2019). "However, the average NOS3 levels presented a bimodal behavior in PCa patients classified according to their tumor stages, with higher levels in the pT2 stage." (PMID 18823560, 2008).
tumor (continued). "The NOS3 transcriptional activity was also highly correlated with disease staging, once its highest level is reached at the pT2 stage, when the angiogenic stimulus is required for tumor cell dissemination and metastasis." (PMID 18823560, 2008). "Additionally, we have evaluated the effect of these five NOS3 SNPs on the mRNA expression levels of the peripheral blood of PCa and BPH patients, and their association with circulating tumor cells in the blood." (PMID 18823560, 2008). "As NOS3 may independently influence oxidative stress and tumor cell behavior, future studies incorporating NOS3 knockdown-only controls in long-term assays and xenograft models will be essential to distinguish its intrinsic biological effects from its contribution to drug responsiveness." (PMID 41233831, 2025). "In addition, patients with higher NOS3 levels were diagnosed with a later tumor stage in COAD." (PMID 33747912, 2021). "Notably, these two NOS3 gene SNPs have been studied in relation to cancers such as breast, prostate, colorectal, and lung cancers, with evidence suggesting that these SNPs may influence tumor progression by modulating NO production and vascularity." (PMID 39859471, 2025). "The results demonstrated that NOS3 and TCIRG1 were highly expressed in tumor cells and samples compared to normal cells and tissues, while GPX3 and DUSP1 were expressed at low levels in tumor cells and samples." (PMID 37124616, 2023). "Another NOS3 inhibitor, N(G)-nitro-L-arginine methyl ester (L-NAME) was also reported to inhibit PAAD tumor growth." (PMID 33747912, 2021). "Three isozymes of NOSs: neuronal NOS (NOS1), inducible NOS (NOS2), and endothelial NOS (NOS3), all contribute to tumor progression through distinct effects of biological regulation on tumorigenesis." (PMID 33859186, 2021). "Objective response rate (complete or partial response) was significantly correlated to tumor microenvironment-related SNPs concerning CCL2, NOS3, IL1RN, IL12B, CXCR3, and IL6R genes." (PMID 32733486, 2020). "NOS3, VEGFR-2, and ANGPT2 levels correlated inversely with tumor reduction after chemotherapy." (PMID 41749831, 2026). "Furthermore, RNA sequencing analysis from TCGA data showed that the expression of NOS3/NOS3 positively correlated with the expression of CSF1, CSF1R, CD163, and several other tumor-promoting immune cell markers in high-grade PCa (Gleason 9)." (PMID 36209194, 2022). "In contrast, the neuronal Nos1 and the endothelial Nos3 gene transcripts were not significantly regulated by type I IFNs, in either tumor cells or leukocytes." (PMID 31481761, 2019). "Finally, NOS3 is nitric oxide (NO) synthetase, and NO plays an important role in various steps of VEGF-mediated tumor angiogenesis, such as dissolution of matrix, cell migration and proliferation, new vascular network construction, and lumen formation." (PMID 31505835, 2019). "Our extended study by using postembedding triple immunogold labeling techniques showed that the clusters of NOS2 positive, but no NOS3 and ET-1 immunopositive containing gold particles were seen in tumor vessel endothelium." (PMID 23691268, 2013). "In the present work, higher NOS3 transcript levels in peripheral blood of positive PCA3 patients than in negative ones suggest that tumor may be in a medium-late (pT2) stage of the disease and corroborates with the molecular approach for disease staging." (PMID 18823560, 2008). "And GAD1, NOS3, SERPINE1, and VWF protein levels were not significantly different in tumor and normal samples." (PMID 36860371, 2023). "NOS3 was never found in tumour cells, but, as expected from the NADPH-d assay, endothelial cells were stained with the NOS3 antibody." (PMID 15150612, 2004).
cancer (60 papers, 2008 to 2026). A tumor composed of atypical neoplastic, often pleomorphic cells that invade other tissues. "The third family (MPT23 and two cancer-free relatives) presented the LP variant in NOS3, which encodes the enzyme endothelial nitric oxide synthase." (PMID 39408606, 2024). "The impact of NOS3 gene polymorphism on cancer is currently a topic of debate, mainly due to factors such as sample size, cancer type, and the influence of ethnic variation." (PMID 38107574, 2023). "The variant TT genotype of a common SNP on NOS3, rs1799983, was associated with a significant decreased risk for low-grade cancer." (PMID 35096612, 2021). "AP2-associated protein kinase 1 (AAK1) and NOS3 were related to the clathrin-mediated endocytosis and cardiovascular-cancer-respiratory pathway, respectively." (PMID 26538867, 2015). "Interestingly, the absence of significant associations between NOS3 SNPs and therapeutic response in this study contrasts the findings in other cancers, where NOS3 polymorphisms have been shown to influence treatment outcomes or prognosis." (PMID 39859471, 2025). "The functional effects of NOS3 polymorphisms—such as altered NO production—could influence these pathways differently in each subtype, potentially contributing to subtype-specific cancer behaviors." (PMID 39859471, 2025). "The main reasons for the ongoing debate about the impact of NOS3 gene polymorphisms on cancer are mainly due to several factors, such as the number of patients included in such research, cancer type, genetic background, and the influence of ethnic variability and environmental factors." (PMID 39859471, 2025). "However, the exact contribution of specific NOS3 polymorphisms to cancer susceptibility is still under investigation." (PMID 39859471, 2025). "According to the literature, there is a total of 168 genetic polymorphisms located within or close to NOS3, of which three have emerged as particularly noteworthy due to their shared impact on reducing NO levels and their established associations with cancer: rs2070744, rs1799983, and rs869109213." (PMID 38785560, 2024). "Epidemiological studies on the role of NOS3 polymorphisms on cancer susceptibility and progression." (PMID 38785560, 2024). "Additionally, many studies have reported that NOS3 gene polymorphisms are associated with risk for cancer progression, cancer susceptibility and drug response." (PMID 33747912, 2021). "Taken together, our results offer a promising foundation for future translational research and highlight the potential of NOS3 rs2070744 as a valuable tool in personalised cancer treatment." (PMID 41528397, 2026). "Incorporating NOS3 rs2070744 into a predictive clinical model increased prognostic precision regarding patient survival by 15% compared to cancer stage alone." (PMID 41528397, 2026). "This duality underscores the complexity of NOS3’s function in cancer and highlights the need for careful interpretation when considering its stabilization as a therapeutic strategy in HCC." (PMID 41233831, 2025). "Nitric oxide is a signaling molecule synthesized by three subtypes of NO synthase (NOS1, NOS2, and NOS3) and is increased in various cancers and involved in various cancer processes, such as proliferation and migration." (PMID 38877096, 2024). "A recent study suggests a link between NOS3 gene and HPV infection, but its association with cancer remains uncertain." (PMID 39334938, 2024). "Up-regulation of NO synthase (NOS3) increases the arginine-citrulline cycle and thus enables the cancer cell to avoid more urea production and to rather utilize the nitrogen to meet the increased demands for nucleic acid." (PMID 37296884, 2023). "It has been observed that NOS3 inhibits apoptosis and promotes angiogenesis, proliferation, invasiveness, and immunosuppression in malignant tumors." (PMID 37894904, 2023). "In this analysis, high-grade cancer regions with higher expression of NOS3 had elevated CSF1, CSF1R, and CD206." (PMID 36209194, 2022).
cancer (continued). "Further analyses in STAD showed that response of STAD cancer cells to QS-11 and brivanib were strongly correlated with NOS3 expression." (PMID 33747912, 2021). "NOS3 has been found to inhibit apoptosis and promote angiogenesis, proliferation, invasiveness, and immunosuppression of malignant tumors." (PMID 33747912, 2021). "In conclusion, this research showed that the expression level and clinical significance of NOS3 was highly cancer-dependent." (PMID 33747912, 2021). "In this sense, the overexpression of miR-335 and miR-543 reduces NOS3 expression, and cell migration and invasiveness in cultured PC-3 cancer cells, being this connection confirmed in patients with metastatic prostate cancer (Figure 3A2)." (PMID 34200849, 2021). "For example, in the C-T network, ICT, kaempferol and sitosterol target proteins associated with inflammation, cancer cell apoptosis and migration in the TME, such as COX2, IL-6, GSK3β, CDK2 and NOS3." (PMID 33460401, 2021). "We investigated the relationship between NOS3 expression and the clinical phenotypes of patients for all cancers and then separately for each cancer type." (PMID 33747912, 2021). "The results of GSEA and GSVA analyses suggested that in STAD, several canonical cancer-related pathways were enriched in higher NOS3 expression group." (PMID 33747912, 2021). "In recent years, NOS3 has been found to play various roles in malignant tumors, such as inhibiting apoptosis and promoting angiogenesis, proliferation, invasiveness, and immunosuppression." (PMID 33747912, 2021). "NOS3 was shown to play a pivotal role in cancer by promoting angiogenesis, metastasis formation and invasiveness, inhibition of apoptosis and immune response." (PMID 34885088, 2021). "Analyses in cancer cell lines showed that NOS3 was expressed at quite high levels in COAD and STAD cell lines." (PMID 33747912, 2021). "Ultimately, the correlation between NOS3 expression level in 664 cancer cells and cell response to 544 drugs was analyzed to explore the potential of NOS3 as a therapeutic target." (PMID 33747912, 2021). "Nitric oxide, a signaling molecule synthesized by three isoforms of NO synthase (NOS1, NOS2 and NOS3), increases in multiple cancers and participates in various cancer processes such as formation, progression and metastasis." (PMID 31805977, 2019). "The basis of our choosing G894T polymorphism among others can be explained as the product of NOS3 is constitutively expressed in endothelial cells and vascular epithelium of the cancer cells." (PMID 26682008, 2016). "Considering the cut-off value, it was observed a 4.0-fold higher chance (CI95%, 0.95 – 16.77; p = 0.12) of having cancer when the NOS3 expression levels were equal or higher than 0.8." (PMID 18823560, 2008). "Similar to NOS3 gene, RNTFT2 expression is associated with poor prognosis in cancer." (PMID 38297316, 2024). "NOS3, ACE, and INSR have high mutation frequencies in most cancer types." (PMID 35513851, 2022). "NOS3 has also been shown to be involved in chemoresistance in cancer." (PMID 35864956, 2022). "However, the research on and application of NOS3-targeted medicine in malignant tumors are still extremely limited." (PMID 33747912, 2021). "In recent years, NOS3 has been found to play various roles in malignant tumors." (PMID 35047513, 2021). "And the expression pattern of NOS3 and its diagnostic and prognostic potential has not been investigated in a pan-cancer perspective." (PMID 33747912, 2021). "In cancer tissues and cancer cell lines, NOS3 mRNA expressed highest in STAD." (PMID 33747912, 2021). "Several canonical cancer-related pathways were found to be correlated with NOS3 expression in STAD." (PMID 33747912, 2021). "Our results are also supported by previous works, which have also indicated that NOS3 levels may present a bimodal behavior during cancer development." (PMID 18823560, 2008).